NRP1 (neuropilin 1)
Diseases named in the same sentence as NRP1 in open-access papers (continued):
Sharing a sentence is not in itself a finding about the gene and the disease.
cervical carcinoma (23 papers, 2011 to 2025). A carcinoma arising from either the exocervical squamous epithelium or the endocervical glandular epithelium. "Under hypoxic conditions in cervical cancer, high expression of neuropilin-1 (Nrp-1) is significantly associated with TAM recruitment and migratory function." (PMID 40264780, 2025). "A refined risk score model, comprising PLA2G7, TNF, TYK2, F2, and NRP1, effectively stratified cervical cancer patients into distinct risk groups." (PMID 37704909, 2023). "NRP1 has been reported to induce tumor-associated macrophage activation and exert pro-tumor effects in cervical cancer under hypoxia." (PMID 37704909, 2023). "The secreted form of NRP-1 (sNRP-1) has been known to inhibit cell associated NRP-1 function in cervical cancer, with circulating sNRP-1 levels in patients with cervical cancer significantly higher than those of controls." (PMID 33395426, 2021). "Previous study have shown that NRP1 was associated with cervical cancer progression and poor survival, suggesting that NRP1 could be an independent prognostic factor in cervical cancer." (PMID 37704909, 2023). "Soluble NRP1 (sNRP) in circulating and NRP1 proteins were associated with cervical cancer stages." (PMID 37704909, 2023). "We observed a significant increase in the expression of multiple immune checkpoints across different risk subtypes of cervical cancer, including CD276 and NRP1." (PMID 40517358, 2025). "Transportin-1 (TNPO1)-induced nuclear import of FUBP1 (Far upstream element binding protein 1) led to tumor immune evasion via upregulation of NRP1 in cervical cancer." (PMID 37704909, 2023). "The presence of Nrp-1 and M2-like TAMs correlated with an increase in the malignant properties of cervical cancer cells, such as lymph node metastasis and poor tumor differentiation." (PMID 36670988, 2023). "The depletion of Nrp1+ Tregs in tumor‐draining lymph nodes was directly related to a favorable response to chemoradiotherapy in cervical cancer." (PMID 35474948, 2022). "have shown that depletion of Nrp1+ Tregs in tumor‐draining lymph nodes is directly related to a favorable response to chemoradiotherapy in cervical cancer." (PMID 35474948, 2022). "A higher frequency of Nrp1(+) T-regs frequency suppresses the immune response against distant cervical cancer cells." (PMID 33671013, 2021). "The authors suggested that the process of NRP-1 upregulation is initiated at early stages of dysplasia formation and the increase of NRP-1 levels correlated with cervical cancer stage and nodal metastases." (PMID 33002021, 2020). "Upregulation of NRP-1 was reported in several cancers: oral squamous cell carcinoma, cervix cancer, hepatocellular cancer." (PMID 33002021, 2020). "Overexpressed Nrp-1 in hypoxia-primed cervical cancer cells was necessary for hypoxic cervical TME to recruit and polarize macrophages towards the M2-like phenotype." (PMID 31284453, 2019). "The results indicate that hypoxic TME play a critical role in activation and pro-tumoral growth by Nrp-1 in cervical cancer." (PMID 31284453, 2019). "Nrp-1 and M2-like TAMs have been shown to be related to the malignant properties of cervical cancer, such as the FIGO stage and lymph node metastasis." (PMID 31284453, 2019). "Immunophenotypic and functional assessment of the immune state in women diagnosed with metastatic cervical cancer versus those still in the early stage of the disease revealed an enrichment of NRP1+ Tregs in the tumor-draining lymph nodes (TDLNs)." (PMID 29067024, 2017). "In summary, this study demonstrated that the levels of circulating sNRP-1 and cell-associated NRP-1 protein were highly increased in patients with CIN and cervical cancer." (PMID 25873749, 2015). "Our results showed that, compared to controls, sNRP-1 and NRP-1 protein levels were frequently upregulated in samples from both cervical cancer and CIN." (PMID 25873749, 2015).
cervical carcinoma (continued). "The expression of NRP-1 protein was significantly increased in both cervical cancer and CIN groups compared with control group (P < 0.01, resp)." (PMID 25873749, 2015). "In cervical cancer, the positive NRP-1 staining can be found in cancer cells, endothelial cells, and immune cells, and the role of these immune cells in cervical cancer is still unclear." (PMID 25873749, 2015). "In this study, we first verified the increased level of sNRP-1 in circulation and the focal expression of NRP-1 protein in a subset of cervical cancerous and precancerous patients by ELISA and IHC, respectively." (PMID 25873749, 2015). "High expression of NRP1 in cervical cancer patients was correlated with shorter OS." (PMID 37704909, 2023). "Moreover, preoperative chemoradiation therapy reduced Treg and Nrp1 + Treg levesl in lymph nodes of cervical cancer patients." (PMID 37704909, 2023). "Similarly, it has been shown that hypoxic cervical cancer cells instruct the recruited macrophages to transform into M2-like TAMs by upregulating Neuropilin-1 (Nrp-1) in hypoxic regions." (PMID 36670988, 2023). "Under exposure to low-pressure atmospheric conditions, such as pO2 at an altitude of 5,000 m, M2-like tumor-associated macrophages (TAMs) activate and significantly increase the population of cervical cancer cells in response to upregulated expression of neuropilin-1 (Nrp-1) and CA IX." (PMID 34957091, 2021). "In addition, NRP1+ Tregs also decreased in patients with advanced cervical cancer receiving a combination of low dose radiation and chemotherapy, in comparison to those who only received chemotherapy." (PMID 29067024, 2017). "This phenomenon suggests that the NRP-1 may play a special role in the tumor-infiltrating immune cells of cervical cancer." (PMID 25873749, 2015). "However, the role of both sNRP-1 and NRP-1 proteins in patients with cervical cancer is still unclear." (PMID 25873749, 2015). "This may implicate sNRP-1 responses to NRP-1 protein in cervical cancer and CIN." (PMID 25873749, 2015). "Neuropilin 1 (NRP1) mediate hypoxic TME-induced activation and the pro-tumoral function of TAMs in cervical cancer." (PMID 32219066, 2020). "In the HPA database, the expression of NRP1 was characterized by weak-to-moderate cytoplasmic positivity, often with a granular pattern in most cancer tissues, but this was negative in carcinoids and several cases of skin and cervical cancers." (PMID 37190154, 2023).
diabetes (22 papers, 2015 to 2025). "Some of NRP1’s ligands have been implicated in diabetes and in DN, but scarce data are available to date." (PMID 34360529, 2021). "We observed evidence of colocalization for observed MR associations for SPON1, CCL15, and FSTL3 with multiple outcomes; for SVEP1 with HF; and for NRP1 with diabetes and CHD." (PMID 38225249, 2024). "Here, we found diabetes reduced NRP1 transcripts in bone marrow pericytes and increased SEMA6A (p < 0.05 vs non-diabetic control individuals for both comparisons), a known angiogenesis inhibitor." (PMID 31001672, 2019). "As nerve and blood vessel growth and regenerative capacities are defective in diabetes, we focused on studying the key regulator of these processes, the neuropilin-1 (NRP-1)/semaphorin pathway." (PMID 27598321, 2016). "We observed MR evidence for associations between genetically regulated levels of 7 proteins and HF risk factors including: SPON1, CCL15, and ITIH3 with hypertension; SVEP1 and SPON1 with atrial fibrillation; FSTL3 and NRP1 with diabetes; and APOF, CCL15, ITIH3, and NRP1 with CHD." (PMID 38225249, 2024). "Inhibitors of these interactions could help elucidate the importance of VEGF‐B/NRP1 signalling in cell homeostasis and may prove useful as treatments in diseases such as cancer and diabetes." (PMID 34647407, 2022). "Thorough investigation of Sem3A and NRP-1 expression in skin of a larger cohort of diabetic subjects suffering from neuropathy would reveal their role in the development of peripheral somatosensory deficits in diabetes." (PMID 27598321, 2016). "Our results thus indicate that NRP-1 might have an important role in the development of SFN or inhibits the regeneration of the epidermal nerve fibers in diabetes." (PMID 27598321, 2016). "The OIR model has been used recently to define the function of NRP1 and its ligands in retinal neovascularisation, whilst a mouse model of diabetes has also been used to study the role of NRP1 and its ligands in diabetic retinopathy and ocular oedema (Section 6)." (PMID 26923176, 2016). "Albeit some of NRPs’ ligands and particularly those of NRP-1 are implicated in diabetes and DN, the role of NRP-1 is not yet completely elucidated." (PMID 26239560, 2015). "We conclude that ATWLPPR, an NRP-1 inhibitor, may reduce the early retinal damage induced by diabetes by preserving vascular integrity and decreasing the oxidative stress level." (PMID 26554379, 2015). "Therefore, it is tempting to speculate that specific targeting of NRP1 in severe SARS-CoV-2 infection may be a potentially useful strategy in patients with diabetes." (PMID 34961486, 2021). "Interestingly, in our study IL-35 administration reduced the numbers of Foxp3+Nrp1+ cells, which may suggest a protective role of IL-35 also in other aspects of diabetes." (PMID 26224624, 2015). "We examined the expression of A2ARs and Sema3a, as well as Neuropilin 1 and Plexin A, the coreceptors of Sema3a, in the dorsal horn of the lumbar spinal cord of an animal model with HFD-induced diabetes." (PMID 32566683, 2020). "In addition, our data suggest that NRP-1 might play an important role in epidermal nerve fiber loss and/or defective regeneration and that NRP-1 receptor could change the epidermal environment to a nerve fiber repellant bed possibly through Sem3A in diabetes." (PMID 27598321, 2016). "Therefore, treatment with the neuropilin-1 inhibitor, ATWLPPR peptide, had protective effects against the abnormal ERG induced by diabetes." (PMID 26554379, 2015).
Obesity (22 papers, 2019 to 2026). Accumulation of substantial excess body fat. "For example, NRP1 has been implicated in macrophage activation during sepsis and in promoting inflammation in obesity-related metabolic diseases." (PMID 40134439, 2025). "Given the metabolic role of BAT during obesity, we investigated the impact of macrophage-resident NRP1 deficiency on the thermogenic function of iBAT in a HFD model of weight gain." (PMID 34344941, 2021). "This is consistent with findings demonstrating that NRP1‐deficient myeloid cells are more pro‐inflammatory, classically activated cells in models of obesity, tumor growth, and sepsis." (PMID 33876574, 2021). "Although ageing also contributes to increased expression of the receptors and co-receptors in AT, ACE2 and NRP1 expression is much more upregulated in obesity." (PMID 40806445, 2025). "NRP1 mRNA expression significantly increases in the subcutaneous AT of patients with obesity and type 2 diabetes." (PMID 40806445, 2025). "ACE2, TMPRSS2, ADAM17, and NRP1 are more expressed in visceral AT, with obesity significantly influencing their protein expression." (PMID 40806445, 2025). "The deletion of the Nrp1 and Flt1 genes renders mice resistant to diet-induced obesity because of less lacteal CM uptake." (PMID 35205322, 2022). "Expression of alternative SARS-CoV-2 entry receptors like CD147, dipeptidyl peptidase 4 (DPP4), and neuropilin 1(NRP1) have been reported in adipocytes and their expression is increased by obesity and decreased by anti-inflammatory myokines." (PMID 36137009, 2022). "While investigating the role of innate immunity in obesity, we previously identified myeloid-resident neuropilin-1 (NRP1) as necessary for healthy weight gain and maintaining glucose tolerance in obesity." (PMID 34344941, 2021). "Given that loss of BAT function can impact the accumulation of body fat, we investigated the effect of a myeloid-specific knockdown of Nrp1 in an experimental model of obesity." (PMID 34344941, 2021). "In sum, our study suggests an indirect role for myeloid cells expressing NRP1 in BAT homeostasis during diet-induced obesity." (PMID 34344941, 2021). "Therefore, the observed variations in ACE2, ADAM17, and NRP1 expression are primarily attributable to obesity itself rather than to confounding effects from underlying conditions or treatments." (PMID 40806445, 2025). "Furthermore, our results also revealed several common upstream regulators associated with immune regulation and resistance to obesity (IL-4, IL-5, IL-33, CD15, HGF, ANGPT2, VEGFA, and neuropilin 1 [Nrp1]), supporting a critical role of intestinal homeostasis in systemic pathogenesis of obesity." (PMID 36880999, 2023). "In women with previous obesity, ACE2 and NRP1 levels decreased, while TMPRSS2 and ADAM17 remained unchanged." (PMID 40806445, 2025). "Conversely, the protein expression levels of ACE2 and NRP1, receptors to which SARS-CoV-2 directly binds, decrease in individuals with previous obesity." (PMID 40806445, 2025). "ACE2, TMPRSS2, and NRP1 positively correlated with BMI in AS and/or E, while NRP1 correlated with age in T. In subcutaneous AT, ACE2 and NRP1 were more influenced by obesity while TMPRSS2 was more age-dependent." (PMID 40806445, 2025). "High VEGF-A signaling by deletion of NRP1 and FLT1 increases zipper-like junctions to make lacteals tighter, lipid uptake lower, which protects against obesity." (PMID 36506056, 2022). "During diet-induced obesity (DIO), myeloid-resident NRP1 influences interscapular BAT mass, and consequently vascular morphology, innervation density and ultimately core body temperature during cold exposure." (PMID 34344941, 2021). "Age alone induces a 4-fold increase in NRP1 protein levels (p = 0.0179 between control and older women without obesity groups)." (PMID 40806445, 2025). "Interestingly, here, a different pattern of expression of the receptors (ACE2 and NRP1) and co-receptors (ADAM17 and TMRPSS2) with obesity and ageing is reported." (PMID 40806445, 2025).
Obesity (continued). "In support of this evidence, a lack of Nrp1 in GnRH neurons in mice leads to obesity, thus revealing the previously unrecognized role of SEMA3A and the GnRH system in maintaining energy homeostasis." (PMID 38541683, 2024).
bladder cancer (17 papers, 2010 to 2026). "On the other hand, cumulating evidence indicates that MAPK signaling activation is associated with VEGF-mediated tumor progression in bladder cancer, which was also observed in epidermal cancer stem cells but in a NRP1-dependent manner to enhance angiogenic potential, invasion and migration." (PMID 34249735, 2021). "Moreover, neuropilin-1 upregulation was associated with shorter overall survival in bladder cancer patients." (PMID 29207682, 2017). "The m6A reader IGF2BP2 facilitates M2 macrophage polarisation and enhances the malignant behaviour of bladder cancer by stabilising NRP1 mRNA expression." (PMID 41527491, 2026). "The latest research shows that SS suppresses neuropilin-1 NRP1 expression in bladder cancer (BD) cells by binding to the b1 domain of the protein on the cell membrane." (PMID 36569285, 2022).
lung adenocarcinoma (16 papers, 2016 to 2025). A carcinoma that arises from the lung and is characterized by the presence of malignant glandular epithelial cells. "In other tumor types some interesting findings have been published, where HIF-1α interacted with the NRP1 promoter in lung adenocarcinoma and induced cell metastasis and vasculogenic mimicry." (PMID 36376373, 2023). "Overall, our results clarify that GATA3 has different regulatory effects on NRP1 in two lung adenocarcinoma cells, and H3K4me3 is also involved." (PMID 35993027, 2022). "Herein, our study explored the role of the HIF-1α/NRP1 axis in mediating lung adenocarcinoma metastasis and VM formation." (PMID 33850110, 2021). "HIF-1α, NRP1 expression, and VM in lung adenocarcinoma (LUAD) patient samples were examined by immunohistochemical staining." (PMID 33850110, 2021). "HIF-1α plays an important role in inducing lung adenocarcinoma cell metastasis and VM formation via upregulation of NRP1." (PMID 33850110, 2021). "High level of NRP1 associates with worse prognosis in multiple cancers, while high level of TMPRSS2 is associated with better survival of Lung Adenocarcinoma (LUAD)." (PMID 34168096, 2021). "This study highlights the potential therapeutic value of targeting NRP1 for suppressing lung adenocarcinoma metastasis and progression." (PMID 33850110, 2021). "Functional consequences of LKB1 deletion was investigated by stably silencing LKB1 expression in NRP-1-positive H1792 metastatic, stage IV lung adenocarcinoma cell line." (PMID 26701889, 2016). "The study suggests that targeting NRP1 could be a valuable therapeutic strategy to prevent lung adenocarcinoma metastasis and progression." (PMID 37298296, 2023). "In a recent study, NRP-1 was also found to be involved in this process in lung adenocarcinoma." (PMID 37298296, 2023). "In summary, we successfully constructed two models of radiation resistance in lung adenocarcinoma cells using the experimental method developed in our lab and demonstrated new evidence for the role of NRP1 in the mechanism of radiation resistance in NSCLC cells." (PMID 34539883, 2021). "In the present study, the TCGA databases were analyzed in order to investigate the connection between YAP and NRP1, r showing a positive connection between YAP and NRP1 in lung adenocarcinoma patients." (PMID 39187525, 2024). "Radiation-resistant cellular models of lung adenocarcinoma show increased NRP1 expression, and the NRP1 inhibitor EG00229 reduces the expression levels and binding capacity of NRP1." (PMID 37894289, 2023). "NRP1 and VEGF-165 expression in tumor tissues and adjacent healthy tissues of 5 patients with lung adenocarcinoma was detected by immunohistochemistry (IHC) and qRT‐PCR." (PMID 34539883, 2021). "Particularly there was a clear difference in correlation of NRP1 expression with infiltrated Treg and M2 macrophages between STAD and lung adenocarcinoma (LUAD)." (PMID 32408477, 2020). "Moreover, the study indicates that MMP2, VE-cadherin, and vimentin are impacted by the mechanisms involved in lung adenocarcinoma cell metastasis and VM formation, with HIF-1α playing a crucial role in this process by upregulating the expression of NRP1." (PMID 37298296, 2023). "We previously demonstrated negative correlation between LKB1 and NRP-1 in lung adenocarcinoma, and confirmed similar findings in a subset (∼33%) of endometrial tumor specimens." (PMID 26701889, 2016). "Thus, EG00229 may reverse the radiation resistance of lung adenocarcinoma cells by inhibiting the binding of NRP1 and VEGF and influencing the expression of NRP1 and VEGF." (PMID 34539883, 2021).